NGF (nerve growth factor)
Diseases named in the same sentence as NGF in open-access papers (continued):
Sharing a sentence is not in itself a finding about the gene and the disease.
asthma (continued). "During the onset of asthma and other allergic diseases, mast cells and eosinophils in the airway can synthesize and secrete NGF, thereby increasing the amount of NGF in the body." (PMID 38049878, 2023). "Some other studies have shown that NGF and its receptors are involved in high bronchial responsiveness, like asthma and allergic rhinitis." (PMID 34502019, 2021). "Inhibition of NGF through NGF-targeting short hairpin RNAs also appeared to reduce the severity of asthma phenotypes." (PMID 34502019, 2021). "Using an ovalbumin (OVA)-induced asthma rat model, it has been found that NGF aggravates inflammation, AHR, and airway remodeling via the Th2 immune response and by increasing matrix metalloproteinase-9 (MMP-9) expression." (PMID 34502019, 2021). "Research on the pathogenesis of asthma in OVA-sensitized mice furnishes proof that NGF blockade reduces airway inflammation." (PMID 34502019, 2021). "The NGF expression was also shown to be up-regulated in other inflammatory diseases such as asthma, arthritis and psoriasis, suggesting a role for this neurotrophin in inflammatory diseases." (PMID 34276280, 2021). "Several studies reported that NGF in the skin and NGF serum levels of AD and psoriatic patients as well as serum levels of patients with asthma are increased." (PMID 33681256, 2021). "Asthma patients demonstrate increased levels of NGF after allergenic bronchial provocation, and NGF levels are also closely related to the severity of the disease." (PMID 34502019, 2021). "In another study, NGF was shown to be a key factor in lung inflammation and Th1/Th2 balance in asthma after respiratory syncytial virus infections." (PMID 34502019, 2021). "NGF, a critical mediator in neuro-immune mechanisms of asthma, aggravates inflammation in asthma and airway remodeling." (PMID 34502019, 2021). "All of these studies show that NGF is a mediator of asthma, and NGF blockade improves some symptoms." (PMID 34502019, 2021). "It has been verified that NGF blockade inhibits airway allergic inflammation via regulating the balance of Th1 and Th2 responses of T cells in experimental asthma models." (PMID 34502019, 2021). "At the same time, a study has shown that the level of NGF is related to the number of eosinophils, which are the main effector cells of asthma." (PMID 34502019, 2021). "NGF, a neurotrophin highly associated with AHR, has also been implicated in other lung diseases in addition to asthma." (PMID 33082140, 2020). "The study of asthma pathogenesis in ovalbumin-sensitized mice provides evidence that NGF blocking decreases inflammation in the airways." (PMID 30939862, 2019). "An elevated NGF level was observed in patients with asthma after allergen bronchial provocation, and was closely related to the severity of the disease." (PMID 30939862, 2019). "It is obvious that the modulation of NGF level, which affects the activity of immune and mast cells, will allow for controlling the inter-systemic relationships in asthma." (PMID 30939862, 2019). "p75NTR activation of pDCs from patients with asthma increased allergen-specific T cell proliferation and cytokine secretion in nerve growth factor concentration-dependent manner." (PMID 28861085, 2017). "Nerve growth factor (NGF), produced by both MCs and eosinophils, is increased in patients with asthma." (PMID 28791287, 2017). "Based on our observations of a pDC-mediated and p75NTR-dependent immune response in mice, we determined the effect of NGF on WT pDCs in experimentally induced asthma." (PMID 28861085, 2017). "The fact that e-vapor containing nicotine affects signaling by NGF and others have shown that nicotine stimulated NGF release contributes to tobacco smoke-induced asthma raises significant questions about prolong use of e-cigarettes in this regard." (PMID 27041137, 2016). "A large body of evidence shows that nerve growth factor (NGF) exerts biological activity on the immune system, thereby influencing allergic diseases and asthma." (PMID 27872863, 2016).
asthma (continued). "Der p2 is shown to induce reactive oxygen species (ROS) and ROS-mediated nerve growth factor (NGF) release from airway epithelium, and NGF was found to be important for the development of asthma features." (PMID 25883597, 2015). "Increased levels of NGF expression are observed in patients with asthma following bronchial provocation with an allergen, and are associated with the severity of the inflammatory process and disease." (PMID 25289030, 2014). "In the present study, the effect of NGF inhibition on the maturation and phenotype of lung DCs was investigated in a mouse model of asthma." (PMID 25289030, 2014). "Quantitative analysis confirmed that the degree of peribronchial inflammation in the anti-NGF group decreased significantly compared with the asthma and control IgG groups (P<0.05)." (PMID 25289030, 2014). "By contrast, levels of IL-4 were reduced significantly, but levels of IFN-γ increased markedly, in the mice of the anti-NGF group when compared with those in the asthma and control-IgG groups." (PMID 25289030, 2014). "In conclusion, the results of the present study provide an explanation for the NGF promoting activation of lung DCs, which undergo maturation and polarization towards a Th2-stimulating phenotype, inducing a Th2 response in asthma." (PMID 25289030, 2014). "However, the mechanisms underlying the effects of NGF on inflammation in asthma remain unclear." (PMID 25289030, 2014). "In children with severe asthma undergoing diagnostic clinical bronchoscopies, NGF levels were significantly elevated in BAL fluid compared to healthy adult controls whose NGF levels were undetectable." (PMID 25296021, 2014). "By contrast, treatment with anti-NGF antibodies significantly reduced the RL when compared with the asthma group; however, a number of RL values in the anti-NGF group mice remained significantly higher compared with those in the control group." (PMID 25289030, 2014). "A marked downregulation in the expression levels of CD80, CD86 and MHC class II was observed in the lung DCs of the mice in the anti-NGF group when compared with the mice in the asthma and control IgG groups." (PMID 25289030, 2014). "The observations of the present study provide new evidence indicating that NGF exacerbates lung inflammation by promoting lung DC maturation and polarization towards a Th2-stimulating phenotype in a mouse model of asthma." (PMID 25289030, 2014). "Nerve growth factor (NGF) is elevated in subjects with allergic asthma, allergic rhinitis, and allergic urticarial–angioedema, with the largest increases observed in asthma." (PMID 25426119, 2014). "AHR, which can clearly indicate acute asthma attacks and is directly affected by NGF, was also reduced by XQLT." (PMID 24010817, 2013). "NGF, the most important growth factor for neuron differentiation, is significantly elevated in asthma." (PMID 22957086, 2012). "Increased serum NGF levels have been found in vernal keratoconjunctivitis, allergic diseases, and asthma." (PMID 23028581, 2012). "In summary, our results present evidence that asthma during pregnancy promotes asthma susceptibility in offspring, and the transformation from AMCC to neuron induced by NGF plays an important role in this process." (PMID 23137120, 2012). "The pregnancy of female rats (dams) with asthma promotes in their pups the differentiation of adrenal medulla chromaffin cells (AMCCs) into sympathetic neurons, mediated by nerve growth factor, which leads to a reduction in epinephrine secretion." (PMID 23137120, 2012). "NGF, an important neurotrophic factor, was shown to increase in asthma and was related to the degree of bronchial hyperreactivity." (PMID 23137120, 2012). "We recently found that asthma during pregnancy induced a tendency toward transformation from AMCCs to sympathetic neurons in offspring rats, which was also related to elevated NGF in the asthmatic dams." (PMID 23137120, 2012).
asthma (continued). "NGF expression and activity is enhanced in asthma, and NGF levels are consistent with the degree of bronchial hyperreactivity." (PMID 22474509, 2012). "We found thatOVA-induced stress in asthma maternal rats during pregnancy enhanced significantlythe serum levels of corticosterone in offspring rats from asthma and NGF maternalgroup from birth to adulthood." (PMID 21647384, 2011). "For example, antibody blockage of NGF affected early inflammatory responses in murine asthma while neutralisation of BDNF reduced only chronic airway obstruction and BHR but not inflammation." (PMID 16441896, 2006). "In agreement with a pathogenic role in allergic asthma, elevated levels of NGF, BDNF and NT-3 have been detected in blood and locally in the airways in patients with asthma, a response that can be further augmented after allergen challenge." (PMID 16441896, 2006). "Compared with patients with asthma and allergy, the levels and increase of NGF are discrete and emphasize the discrepancy between these two conditions, though these groups have similar airway symptoms and are often confused." (PMID 16002371, 2005). "Increased levels of NGF have been found in the serum, bronchial tissue, and bronchoalveolar fluid of patients with allergy and asthma." (PMID 16002371, 2005). "Furthermore, the expression of NGF gene was significantly up-regulated in both the Asthma and the Asthma + PM group at first." (PMID 38273268, 2024). "This indicates that vitamin D may activate the Nrf2/HO-1 signaling pathway in a PM-exposed asthma model, thereby reducing NGF’s expression." (PMID 38273268, 2024). "In vivo experiments preliminarily indicated that vitamin D might activate the Nrf2/HO-1 signaling pathway in the PM-exposed asthma model, thereby reducing NGF’s expression." (PMID 38273268, 2024). "Interestingly, patients with ARC who also presented with asthma showed even higher levels of NGF than patients with solely ARC." (PMID 37047077, 2023). "In asthma, neurons of the autonomous nervous system join spinal nociceptive fibers to innervate the lung: in particular, TrkB-positive parasympathetic vagal fibers and NGF-dependent sympathetic neurons." (PMID 37047077, 2023). "What we can do is monitor asthma disease indicators when treating with NGF." (PMID 38049878, 2023). "NT-3 also might play a role in allergic asthma as levels in BALF of asthma patients after allergen provocation have been found to be elevated, which has previously also been described for NGF and BDNF." (PMID 37047077, 2023). "The potential effect of the RSV-induced upregulation of NGF must also be considered as a pathogenic mechanism in the onset of non-atopic asthma." (PMID 36204661, 2022). "NGF can also affect the function of plasma cells in the development of asthma." (PMID 35784284, 2022). "Suppression of NGF could reduce Th2 immune response, decrease inflammatory infiltration and airway response in murine asthma model." (PMID 35784284, 2022). "Furthermore, capsaicin induced a cough reflex and increased nerve growth factor (NGF) in nasal lavage fluids of patients with asthma-like symptoms." (PMID 36278231, 2022). "This suggests that PF, PH, asthma, NSCLC, and COPD are associated with NGF." (PMID 34502019, 2021). "NGF partakes in the pathogenesis of an OVA-sensitized asthma mouse model." (PMID 34502019, 2021). "Several NGF-activated pathways in asthma have been identified." (PMID 34502019, 2021). "Because miR-98 is a known regulator of PPARγ, a transcription factor that plays a key role in mediating airway remodeling in prenatal nicotine exposure, we focused on examining the potential role of miR-98 in regulating NGF in airway remodeling and asthma therapy." (PMID 33082140, 2020). "In this regard, NGF can be one of the targets of PEA in asthma therapy." (PMID 30939862, 2019).
asthma (continued). "It has been reported that the length of substance P immuno-reactive nerve fibers are increased in airway of allergic conditions such as asthma and that NGF and TNFα secreted by activated mast cells could enhance neuronal outgrowth." (PMID 31275114, 2019). "NGF is considered in close connection with asthma pathogenesis." (PMID 30939862, 2019). "However, it is worth noting that the mechanism for the participation of NGF in the pathophysiology of chronic inflammation in asthma remains not fully understood, and is relevant for further research." (PMID 30939862, 2019). "Nerve growth factor (NGF) and dendritic cells (DCs) have been hypothesized to modulate T cell responses in a mouse model of asthma." (PMID 25289030, 2014). "In addition to its classical nervous system domain, nerve growth factor (NGF) is regarded as an important factor involved in the pathogenesis of allergic diseases, including asthma." (PMID 25289030, 2014). "Since NGF can amplify Th2 response as mention above, the present study hypothesized that NGF may be involved in regulating lung DCs maturation and differentiation during the pathogenesis of asthma." (PMID 25289030, 2014). "The evidence presented that animals exposed to nicotine, human smokers, and children with severe asthma all have elevated NGF levels in their BAL fluid support the concept that nicotine may be a responsible agent in cigarette smoke that induces NGF expression." (PMID 25296021, 2014). "However, decreased expression levels of CD80, CD86 and MHC class II were observed in the lung DCs of the mice in the anti-NGF group, as compared with those in the asthma and control-IgG groups, despite increased serum levels of IFN-γ." (PMID 25289030, 2014). "In addition, NGF and TRK-A have been implicated in a variety of inflammatory and allergic conditions, including asthma and polymorphonuclear leukocyte chemotaxis." (PMID 24386191, 2013). "Also, NGF is an inducible survival growth factor for T cells, depending on the cytokine profile; anti-NGF treatment enhances Foxp3+ regulatory T cells and decreases Th17 cells in a murine model of asthma." (PMID 24223945, 2013). "In support of our hypothesis, Noga and colleagues reported that NGF activates Trk A-positive human monocyte-derived dendritic cells to mediate asthma." (PMID 23672639, 2013). "On the other hand, NGF levels were found increased in asthma patients." (PMID 23137120, 2012). "Since serum NGF levels are found to increase in several systemic diseases including psychosocial stress, allergy, asthma, and autoimmune diseases, measurement of serum NGF in addition to urinary NGF might provide an insight to this mysterious bladder disorder." (PMID 23028581, 2012). "NGF, one of the most important neurotrophic factors involved in neuronal growth, survival, and differentiation, has been clinically detected as increased in asthma patients." (PMID 22957086, 2012). "Circulating NGF levels areincreased in humans with allergic diseases and asthma." (PMID 21647384, 2011). "At present, there is no consensus on the lowest dose of NGF to cause asthma." (PMID 38049878, 2023). "Meanwhile, NGF could aggravate asthma by increasing the level of MMP-9." (PMID 34502019, 2021). "Therefore, NGF has also been deemed a significant factor in the pathogenesis of asthma." (PMID 34502019, 2021). "Overall, the results presented here support the hypothesis that nicotine has a pathophysiologic role in cigarette smoke associated AHR by increasing NGF expression in the lung milieu and shifting ASM cells towards a contractile phenotype making airways with asthma more resistant to control." (PMID 25296021, 2014). "Furthermore, a previous study demonstrated that NGF may exacerbate allergic lung inflammation in an animal model of asthma." (PMID 25289030, 2014). "Therefore, anti-NGF is potentially beneficial for preventing and treating patients with asthma." (PMID 24223654, 2013).
asthma (continued). "Moreover, NGF expression appeared to correlate with the degree of bronchial hyperreactivity; although, the exact mechanism and physiologic implication remained unknown." (PMID 22957086, 2012). "The different growth factors involved in the pathophysiology of asthma include PAF, transforming growth factor (TGF-β), nerve growth factor (NGF), fibroblast growth factor (FGF), epidermal growth factor (EGF), and insulin-like growth factor 1 (IGF-1)." (PMID 37233255, 2023). "NGF exacerbates inflammation and airway remodeling by enhancing Th2 in OVA sensitized asthma in rat model." (PMID 35784284, 2022). "There is a relationship between NGF and TIMP-1 because of the high expression of tissue inhibitors of NGF and TIMP-1 and the correlation between these parameters in asthma patients." (PMID 34502019, 2021). "Later, other researchers investigated the impact of NGF inhibition on AHR and other asthma phenotypes in an asthma mouse model." (PMID 34502019, 2021). "Therefore, NGF may promote the maturation and polarization towards a Th2-stimulating phenotype of activated DCs, contributing to an amplification of the Th2 response in asthma." (PMID 25289030, 2014). "The increased NGF levels in bronchoalveolar lavage samples from smokers and asthmatics are consistent with previous studies and emphasize the potential clinical significance of enhanced NGF signaling in AHR and asthma." (PMID 25296021, 2014). "Among the patients in our study, the lower basal NGF levels in NAL may seem surprising, but this finding underlines that patients with SHR do not have mucosal inflammation, which is probably the main source of high airway NGF levels in asthma and allergy sufferers." (PMID 16002371, 2005). "Eosinophils produce and secrete fibrogenic factors, such as fibroblast growth factor (FGF), heparin binding epidermal growth factor, IL-4, IL-13, IL-17, nerve growth factor, platelet derived growth factor, and transforming growth factor-β (TGF-β), leading to the development of severe asthma." (PMID 36107283, 2023). "Anti-NGF improves AHR and relieves asthma attacks in mice by downregulating the RhoA pathway." (PMID 34502019, 2021). "Therefore, anti-NGF possibly improves AHR and relieves asthma attacks in mice via downregulating the RhoA pathway." (PMID 34502019, 2021). "A high expression of NGF and tissue inhibitor of metalloproteinase-1 (TIMP-1), as well as the correlation between parameters in asthma patients, indicate a possible relationship between NGF and TIMP-1, which may play an important role in asthma pathogenesis." (PMID 30939862, 2019). "Elevated levels of bradykinin and nerve growth factor (NGF) are found in bronchoalveolar lavage of asthma and rhinitis patients while elevated 4-HNE and acrolein are detected in lungs, air spaces, breath, sputum and blood of asthma and COPD patients." (PMID 27827953, 2016). "Since NGF and other neurotrophin have been reported to be factors that are involved in asthmatic reactions, XQLT may influence allergic reactions in asthma by regulating neurotrophin." (PMID 24010817, 2013). "By regulating BALF NGF, TARC and serum BDNF levels, XQLT may control allergic inflammation and eosinophil infiltration in both the early and the late phases of asthma." (PMID 24010817, 2013). "Whereas serum NGF levels can be down-regulated by corticosteroid in asthma, immunomodulating drugs do not appear to reduce NGF levels in rheumatoid arthritis or primary Sjögren's's syndrome." (PMID 21085492, 2010). "The high expression of tissue inhibitors of NGF and metalloproteinase-1 (TIMP-1) and the correlation between parameters of asthma patients show that there may be a relationship between NGF and TIMP-1, which may play a significant role in the pathogenesis of asthma." (PMID 34502019, 2021).